NLRP3 (NLR family pyrin domain containing 3)
Diseases named in the same sentence as NLRP3 in open-access papers (continued):
Sharing a sentence is not in itself a finding about the gene and the disease.
Chagas disease (3 papers, 2013 to 2020). A parasitic infection caused by Trypanosoma cruzi. "IL‐1β and NLRP3 upregulation has been reported in patients’ indeterminate clinical form of Chagas disease." (PMID 32508013, 2020). "In this study, we have utilized wild-type (WT), ASC−/−, and NLRP3−/− macrophages and inhibition approaches to investigate the mechanisms of inflammasome activation and their role in Trypanosoma cruzi infection." (PMID 25372293, 2014). "This manuscript describes original studies on the involvement of NLRP3 inflammasome in the control of Trypanosoma cruzi, the etiological agent of Chagas disease, a chronic infectious illness that affects millions of people in the world." (PMID 24098823, 2013). "Moreover, single nucleotide polymorphism association analysis revealed that Chagas disease presenting Chagas cardiomyopathy is associated with inflammasome genes, including NLRP1 and CARD; however, NLRP3 was not investigated in this study." (PMID 32508013, 2020).
Chlamydial infections (3 papers, 2017 to 2025). "Only minimal chlamydial 16s mRNA signals were detected by ISH in submucosal macrophages of chronically infected mice, indicating NLRP3 macrophage inflammasome activation occurred independently of chlamydial infection." (PMID 34526512, 2021). "Other bacteria, such as Chlamydia pneumonia and Salmonella typhimurium can induce NLRP3 via Caspase-11 macrophages and cause mitochondrial dysfunction." (PMID 28579962, 2017). "Chlamydial infections such as C. pneumoniae developed immune events through the INFα/β, TNF-α, MAPK/ERK, NLRP3/ASC/caspase- 1, JAK/STAT, PI3 K/Akt signaling pathways." (PMID 40275124, 2025). "CtD infected NLRP3−/−, Casp1/11−/−, IL-1β−/−IL-18−/−, and IL-1R−/− mice all exhibited significantly greater infectious loads at day 3 and 7 pi showing NLRP3/Caspase1 inflammasome signaling pathway is critical for controlling early chlamydial infection." (PMID 34526512, 2021).
cholangiocarcinoma (3 papers, 2020 to 2023). A carcinoma that arises from the intrahepatic biliary tree (intrahepatic cholangiocarcinoma) or from the junction, or adjacent to the junction, of the right and left hepatic ducts (hilar cholangiocarcinoma). "The development of cholangiocarcinoma has been linked to a lower NLRP3 expression in BECs." (PMID 37891577, 2023). "Although these studies propend for a protective role of NLRP3 against bile carcinogenesis, further efforts are needed to bridge this pathway to the onset of cholangiocarcinoma." (PMID 37891577, 2023). "Besides immune cells, NLRP3 component of inflammasome is expressed in biliary epithelial cells in primary sclerosing cholangitis, and its lower expression during time and insufficient signaling may be associated with the development of cholangiocarcinoma." (PMID 32707678, 2020). "Interestingly, higher levels of NLRP3 expression were also detected in PSC patients with UC than in PSC patients without UC, while patients developing cholangiocarcinoma showed lower levels of NLRP3." (PMID 32192118, 2020).
Cholestatic liver disease (3 papers, 2020 to 2025). "The present study demonstrated that clusterin deficiency promotes cholestatic liver disease by inducing ER stress and NLRP3 inflammasome activation and that clusterin inhibits ER stress-induced NLRP3 inflammasome activation." (PMID 40089787, 2025). "A number of in vitro and in vivo experiments have started to shed light on the molecular mechanisms behind NLRP3 activation and regulation in the context of cholestatic liver disease." (PMID 32192118, 2020). "As the most fully characterized inflammasome thus far, the role of the NLRP3 inflammasome in cholestatic liver disease may require further study." (PMID 35095513, 2021).
chromoblastomycosis (3 papers, 2017 to 2025). "In conclusion, the present data demonstrate, for the first time, that the inflammasome is activated and that NLRP3 and caspase-1 mediated the F. pedrosoi-induced production of IL-18, which promotes the Th-1-mediated immune response during chromoblastomycosis." (PMID 40315193, 2025).
chronic hepatitis B (3 papers, 2022 to 2025). "For instance, MALAT1 was linked to liver inflammation through activation of the NLRP3 inflammatory complex in patients with chronic hepatitis B and NAFLD." (PMID 40002783, 2025).
chronic lung disease (3 papers, 2020 to 2023). According to the definitions of the American and British Thoracic Societies, including pulmonary functional tests, X-rays, and CT scans for items such as fibrosis, bronchiectasis, bullae, emphysema, nodular or lymphomatous abnormalities. "Previous studies have shown that deficiency in macrophage autophagy strengthens NLRP3 inflammasome activation and silica exposure‐induced chronic lung disease, as well as promoting angiotensin II‐induced inflammation and cardiac fibrosis." (PMID 33043596, 2020). "NLRP3 is not only involved in LPS-induced ALI, but also in ARDS caused by mechanical ventilation, COPD, and other chronic lung diseases." (PMID 36051498, 2022).
chronic multifocal osteomyelitis (3 papers, 2014 to 2023). "Although the etiology of chronic non-bacterial osteomyelitis is still unknown, deficiency of IL-1β receptor antagonist and neonatal-onset multisystem inflammatory disease are caused by mutations in the IL1RN and NLRP3 genes, respectively, and result in over-activation of the IL-1β pathway." (PMID 24973754, 2014).
edema (3 papers, 2021 to 2025). An abnormal accumulation of fluid beneath the skin, or in one or more cavities of the body. "Pulmonary NLRP3 expression was significantly elevated at 4 h post-FE, suggesting NLRP3′s potential involvement in FE-induced lung edema and pulmonary damage." (PMID 40806699, 2025). "Interfering with PTPN22 can reduce the expression of IL-1β and IL-18 by inhibiting the activation of the NLRP3 inflammasome to reduce inflammatory responses, thereby improving neurological dysfunction and reducing cerebral edema in ICH rats." (PMID 36558410, 2022). "As a critical component of innate immunity upon tissue injury, the NLRP3 inflammasome is activated after ICH, thus promoting neuroinflammation and aggravating brain edema." (PMID 36558410, 2022).
fungal keratitis (3 papers, 2021 to 2023). "Activation of NLRP3/pyroptosis was also observed in Candida albicans keratitis, and knockdown of NLRP3 significantly alleviated the pyroptosis and corneal inflammatory response, making it an attractive target for the treatment of fungal keratitis." (PMID 37180116, 2023). "Importantly, compared with that in the Ad-GFP-shRNA group, fungal keratitis with Ad-NLRP3-shRNA treatment showed much less corneal inflammation and clinical scores." (PMID 35463001, 2022). "Hence, tightly regulating the NLRP3 inflammasome-mediated pyroptosis pathway would suggest new intervention strategies to inhibit corneal inflammation and ameliorate blinding fungal keratitis." (PMID 35463001, 2022). "TSLP induces caspase-1–dependent pyroptosis through activation of the NLRP3 inflammasome, suggesting that it may be a potential target for fungal keratitis." (PMID 34925047, 2021). "Therefore, This NLRP3 inflammasome-dependent pathway may be an attractive target for the treatment of fungal keratitis." (PMID 35463001, 2022). "Thus, blocking the activation of the NLRP3 inflammasome-mediated pyroptosis pathway may provide a new therapeutic strategy for fungal keratitis." (PMID 35463001, 2022). "Moreover, whether the NLRP3 inflammasome affects pyroptosis in fungal keratitis remains uncertain." (PMID 35463001, 2022).
gastric tumor (3 papers, 2021 to 2022). "Considering that NLRP3 activity is mediated via inflammasome complexes, and the gastric tumor phenotype in gp130F/F mice is associated with inflammasome activation, we investigated whether the ablation of NLRP3 affected inflammasome activation during gastric tumorigenesis." (PMID 35299732, 2022). "At 3 months of age (early-stage tumorigenesis), the stomachs and gastric tumors of gp130F/F:Nlrp3-/- mice were comparable in size and weight compared to age-matched gp130F/F littermate mice, as was the incidence of tumors." (PMID 35299732, 2022). "However, immunohistochemistry indicated similar PCNA+ proliferating cell numbers in the epithelium of gastric tumors of gp130F/F and gp130F/F:Nlrp3-/- 3mo and 6mo mice." (PMID 35299732, 2022). "Also, similar numbers of apoptotic cleaved Caspase-3+ and cleaved Caspase-8+ cells were observed in 3mo and 6mo gp130F/F and gp130F/F:Nlrp3-/- mouse gastric tumors." (PMID 35299732, 2022). "Similarly, gastric tumorigenesis was also comparable in gp130F/F:Nlrp3-/- and gp130F/F mice at 6 months of age (late-stage tumorigenesis), as evidenced by comparable stomach size and gastric tumor burden and incidence among age-matched mice of both genotypes." (PMID 35299732, 2022). "Also, immunoblotting indicated comparable protein levels of ASC among gp130F/F versus gp130F/F:Nlrp3-/- gastric tumor lysates." (PMID 35299732, 2022). "Furthermore, inflammasome activation levels, determined by immunoblotting and immunohistochemistry for cleaved Caspase-1, which along with ASC is another integral component of inflammasome complexes, were unchanged in gp130F/F and gp130F/F:Nlrp3-/- gastric tumors." (PMID 35299732, 2022). "In gastric tumors of gp130F/F mice, although NLRP3 expression was elevated at the mRNA (qPCR) and protein (immunohistochemistry) levels, genetic ablation of NLRP3 in gp130F/F:Nlrp3-/- mice did not alleviate the development of gastric tumors." (PMID 35299732, 2022). "We also note that the expression of several angiogenesis-related genes (Cxcl1, Cxcl2, Mmp2, Mmp9, and Vegf) was comparable among gastric tumor and non-tumor tissues from 3mo and 6mo gp130F/F and gp130F/F:Nlrp3-/- mice." (PMID 35299732, 2022). "Analysis of intestinal-type GC patient data within The Cancer Genome Atlas (TCGA) revealed that NLRP3 mRNA levels were comparable between total gastric tumor tissues of patients (n = 375) compared to non-tumor gastric tissues (n = 32)." (PMID 35299732, 2022). "Furthermore, phosphorylation levels of NF-κB, which is activated downstream of inflammasomes to promote gastric tumorigenesis in the gp130F/F model, were also similar between gp130F/F and gp130F/F:Nlrp3-/- gastric tumor or non-tumor samples." (PMID 35299732, 2022). "Immunoblotting demonstrated that Caspase-1 activation levels, measured by detection of the cleavage of pro-Caspase-1 (p45) to its mature form (p20 subunit), were comparable between either gastric tumor or non-tumor tissues from gp130F/F:Nlrp3-/- and gp130F/F mice." (PMID 35299732, 2022). "In addition, NLRP3 expression was similar in gastric tumor tissues compared to their paired adjacent non-tumor tissues (n = 27)." (PMID 35299732, 2022).
Hashimoto thyroiditis (3 papers, 2019 to 2024). An autoimmune disorder caused by the production of autoantibodies against thyroid tissue. "Bacteroides fragilis activates the NLRP3 expression, which is overexpressed in the thyroid tissue of Hashimoto's thyroiditis patients." (PMID 38476943, 2024).
Helicobacter infection (3 papers, 2023 to 2025). "GES-1 cells and Helicobacter infection in vivo aggravate the inflammatory response by down-regulating AKT and increasing NF-κB, which induce NLRP3, pro-IL-1β, IL-1β, and IL-18." (PMID 40264171, 2025).
Hyperoxaluria (3 papers, 2021 to 2024). Increased excretion of oxalates in the urine. "Studies have found that a high expression of TXNIP occurs in the kidney of rats with hyperoxaluria and CaOx kidney stones and induces the activation of NLRP3 inflammasome, showing a strong inflammatory response." (PMID 39768161, 2024). "Hyperoxaluria-induced renal NLRP3 upregulation and increased caspase-1 activity and renal content of IL-1β in HP kidneys were reduced by TRPV1 inhibition." (PMID 34201387, 2021). "Interestingly, inhibition of TRPV1 attenuates oxalate- or hyperoxaluria-induced NLRP3 upregulation." (PMID 34201387, 2021). "Another study found that in the mouse model of ethylene glycol induced hyperoxaluria, TXNIP, NLRP3, caspase-1, and other genes were significantly upregulated when CaOx crystal deposition began in the kidney of the mice." (PMID 39768161, 2024). "Because there were parallel changes in TRPV1, ALOX12, and NLRP3 expression as well as caspase-1 activation and IL-1β formation in HP kidneys, we examined whether inhibition of TRPV1 would ameliorate hyperoxaluria-induced renal inflammation and tubular injury." (PMID 34201387, 2021). "Additionally, NLRP3 activation contributed to robust ROS production and inflammatory responses via TXNIP in subjects with hyperoxaluria and in a kidney CaOx rat model." (PMID 34512861, 2021).
ileitis (3 papers, 2023 to 2024). "Therefore, the P2X7 receptor, an activator of the NLRP3 inflammasome, plays a crucial role in determining susceptibility to congenital toxoplasmosis and ileitis." (PMID 39548522, 2024). "The P2X7 receptor regulates the upregulation of NLRP3 and IL-1β and the downregulation of nitric oxide (NO) following ileitis in T. gondii-infected mice." (PMID 39548522, 2024). "Changes in the types and quantities of gut microbiota collectively led to more severe ileitis and more severe disruption of the intestinal mechanical barrier in alcohol‐fed Nlrp3−/− mice." (PMID 39605303, 2024). "We compared alterations in gut microbiota, ileitis, and adhesion protein expression, to analyze the role and potential mechanism of NLRP3 in the early onset of ALD." (PMID 39605303, 2024). "As T. gondii-induced ileitis upregulated inflammasome mRNA, we measured the protein expression levels of NLRP3 and IL-1β in the ileal tissue." (PMID 36831091, 2023).
infectious arthritis (3 papers, 2008 to 2024). "The co‐expression and localization levels of MCT4, GLUT1, IL‐1β, NLRP3, MMP3, and p‐NF‐κB increased by the 14‐day timepoint in chondrocytes and immune cells in our in vivo model of septic arthritis." (PMID 36354099, 2022).
insomnia (3 papers, 2023 to 2025). A sleep disorder characterized by difficulty in falling asleep and/or remaining asleep. "In a study of patients with insomnia with objective short sleep duration, increases in plasma levels of NLRP3 were associated with less total sleep time and longer wake after sleep onset times." (PMID 36470166, 2023).
intestinal cancer (3 papers, 2020 to 2025). "We evaluated its impact on cell migration ability, revealing that reducing NLRP3 expression effectively inhibits bowel cancer cell proliferation." (PMID 39744485, 2025). "The scratch and Transwell assay results indicated that downregulating NLRP3 expression significantly affected bowel cancer cell migration." (PMID 39744485, 2025). "Dysregulation of NLRP3 may contribute to inflammatory diseases and intestinal cancers." (PMID 38182564, 2024). "Furthermore, linear correlation analysis showed a positive correlation between the mRNA expression of NLRP3 and GLI1 in bowel cancer tissue." (PMID 39744485, 2025). "Deep proteomic analysis of a panel of 50 intestinal cancer cell lines shows that caspase-4 and GSDMD are constitutively expressed, while NLR family pyrin domain containing 3 (NLRP3), gasdermin E (GSDME), and caspase-5 are undetectable under standard growth conditions." (PMID 33378358, 2020).
intracranial aneurysm (3 papers, 2023 to 2024). "The NLRP3 inflammasome, a cytoplasmic multiprotein complex, has been demonstrated to exert a pivotal role in neuroinflammation and intracranial aneurysm rupture." (PMID 36875102, 2023). "The NLRP3/MMP9 pathway induces VSMC apoptosis and elastic fiber degradation, contributing to the progression of intracranial aneurysms." (PMID 38992615, 2024).
invasive ductal carcinoma (3 papers, 2021 to 2023). "They found that NLRP3 and ASC proteins were significantly activated in invasive ductal carcinoma cells and patients with higher NLRP3 expression acted out worse 5-year DFS." (PMID 38031068, 2023). "NLRP3 over-expression was observed in invasive ductal carcinoma (IDC; p = 0.012) and in ER and progesteron receptor (PgR) positive cases (p < 0.0001 for both)." (PMID 35745570, 2022). "NLRP3 over-expression was observed in invasive ductal carcinoma (IDC; p = 0.020)." (PMID 34540671, 2021).
ischemic cardiomyopathy (3 papers, 2018 to 2025). Ischemic cardiomyopathy is a cardiomyopathy in which a weakness in the muscle of the heart due to inadequate oxygen delivery to the myocardium with coronary artery disease being the most common cause. "A number of studies have illustrated a central role of NLRP3 inflammasome in murine models of ischemic and non-ischemic cardiomyopathies." (PMID 30150941, 2018). "Thus there is accumulating evidence pointing to a critical role of NLRP3 inflammasome activation in ischemic and non-ischemic cardiomyopathy." (PMID 30150941, 2018). "An augmented function of NLRP3 inflammasome has been proposed to play a role in multiple human diseases, such as auto-inflammatory disease, diabetes, atherosclerosis, and ischemic cardiomyopathy." (PMID 30150941, 2018).
keratitis fugax hereditaria (3 papers, 2022 to 2026). "Patient #7, with slowly progressing TMD, had the heterozygous c.61G>C; p.(Asp21His) variant in NLRP3, causing dominantly inherited keratitis fugax hereditaria (KFH)." (PMID 40387305, 2026). "Recently, two new syndromes have been described associated with NLRP3, namely, Deafness Autosomal dominant 34 (DFN 34) with exclusive cochlear inflammation and Keratitis fugax hereditaria (KFH) with exclusive anterior uveitis." (PMID 40757135, 2025). "During recent years, two new hereditary NLRP3-related disorders have been described, deafness autosomal dominant 34 (DFN34) and keratitis fugax hereditaria (KFH), with an exclusive cochlear- and anterior eye- restricted autoinflammation, respectively, and caused by mutations in NLRP3 gene." (PMID 36275641, 2022).
legionellosis (3 papers, 2020 to 2025). Any disease caused by Legionella bacteria. "Nlrp3−/− or Casp1−/− BMDCs infected with T4SS+Legionella exhibited WT levels of cell death, indicating that while NLRP3 and caspase-1 drive IL-1β release, they are not required for DC death during Legionella infection." (PMID 40530878, 2025).
lentivirus infection (3 papers, 2014 to 2021). Virus diseases caused by the Lentivirus genus. "NLRP3 inflammasome activation was an early and integral aspect of lentivirus infection of microglia, which was associated with lentivirus-induced brain disease." (PMID 24886384, 2014).